MIR6747 (microRNA 6747)
Synonyms: hsa-mir-6747
Gene: MicroRNA gene on chromosome 11 (62,567,011 to 62,567,071, reverse strand). Ensembl gene ENSG00000276102.
Homologues: Orthologues: chimpanzee MIR6747 (100% identical).